FGF23 (fibroblast growth factor 23)
Diseases named in the same sentence as FGF23 in open-access papers (continued):
Sharing a sentence is not in itself a finding about the gene and the disease.
iron deficiency (continued). "In vivo, other positive regulators of FGF-23 include inflammatory related cytokines such as IL-1β, TNF-α, lipopolysaccharides (LPS), mineral mediators like parathyroid hormone (PTH), 1,25(OH)2D and hematopoietic factors such as hypoxia or iron deficiency." (PMID 36246903, 2022). "In addition, iron deficiency and inflammation stabilize hypoxia-inducible factor 1 α (HIF1α) that bind to HIF-binding sites in the promotor of FGF23 stimulating its transcriptional activity." (PMID 34536161, 2021). "For non-classical FGF23 regulation this is not as straightforward, as inflammation or iron deficiency will not only result in higher FGF23 expression but also in increased cleavage." (PMID 33716961, 2021). "The cFGF23 fragments that are increased during iron deficiency and inflammation, do not seem to represent the classical role of FGF23 in maintaining mineral homeostasis." (PMID 33716961, 2021). "A previous report indicated that both C-terminal and intact FGF23 were elevated in ADHR patients with iron deficiency, while normal subjects with iron deficiency showed an increase only in C-terminal FGF23 but not in intact FGF23." (PMID 34901334, 2021). "Iron deficiency, inflammation, and EPO have been shown to increase FGF23 levels and cleavage; and conversely, FGF23, particularly in CKD, may promote anemia, iron deficiency, and inflammation." (PMID 33392212, 2020). "Therefore, we aimed to determine the associations between iron deficiency and higher EPO levels with mortality, and the potential mediating role of FGF23, in a cohort of community-dwelling subjects." (PMID 31170159, 2019). "Notably, iron deficiency, high endogenous EPO, or administration of rhEPO still resulted in increased total FGF23 production and cleavage in CKD." (PMID 30971944, 2019). "Because functional iron deficiency often occurs in states of EPO-mediated erythropoiesis, we also analyzed whether the positive association between EPO and FGF23 might be, at least in part, mediated by TSAT and sTfR." (PMID 31170159, 2019). "Similar to iron deficiency, recent studies from our group and others have established that both endogenous and exogenous EPO may influence FGF23 production and metabolism in CKD patients." (PMID 31170159, 2019). "Iron deficiency itself causes an increased FGF-23 transcription, which does not normally result in hypophosphatemia because of simultaneously increased cleavage and deactivation of iFGF-23." (PMID 27907058, 2016). "Studies on genetic hypophosphatemic disorders indicate the existence of a robust link between iron deficiency and FGF23, although the exact regulatory mechanism is not known." (PMID 24373521, 2013). "However, in the subgroup of our cohort with iron parameters, those with iron deficiency did not have a higher prevalence of anemia or higher total FGF23 concentrations, arguing against a high degree of confounding." (PMID 37752381, 2024). "In addition, elevated levels of FGF23 have been observed in patients with CKD and iron deficiency." (PMID 38732094, 2024). "In addition to iron deficiency and inflammation, EPO is shown to increase FGF23 production." (PMID 36831276, 2023). "Therefore, iron deficiency, which is common in pediatric patients with CKD, may represent a novel factor contributing to elevated intact FGF23 levels in CKD." (PMID 35237863, 2022). "In non-CKD models, iron deficiency concurrently increases Fgf23 mRNA transcription and FGF23 post-translational proteolytic cleavage, resulting in cellular secretion of large quantities of FGF23 protein fragments." (PMID 35461329, 2022). "The associations we observed between functional iron deficiency, high EPO levels, and mortality led us to explore FGF23 as a potential downstream factor mediating these associations, given accumulating evidence supporting a direct relationship between iron status, EPO, and FGF23 metabolism." (PMID 31170159, 2019).
iron deficiency (continued). "Summarizing, inflammation does augment both FGF23 expression and its cleavage, by increased HIF1α expression and stabilization and increased furin activity, but also via hepcidin-induced functional iron deficiency and subsequent non-hypoxic HIF1α stabilization." (PMID 30971944, 2019). "In particular, mice with nutritional iron deficiency could have either high or low FGF-23, indicating that this is not a useful marker of iron deficiency during malaria." (PMID 29338760, 2018). "However, functional iron deficiency induced by hepcidin injection in wild-type mice significantly up-regulated FGF23 mRNA and increased serum c-FGF23 revels, while i-FGF23 levels were not elevated in this model." (PMID 28475601, 2017). "However, a clinical study of non-CKD women with absolute iron deficiency due to uterine bleeding showed only c-FGF23 elevation and their i-FGF23 levels were unchanged." (PMID 28475601, 2017). "The tendency towards a lower BMI in LI mothers compared with the NI mothers raises the possibility that poor overall nutrition during pregnancy rather than specifically iron deficiency may be responsible for the FGF23 effects in infancy." (PMID 26453792, 2016). "Similarly, in female patients with iron deficient anemia markedly elevated C-terminal FGF23 (cFGF23) levels but not intact FGF23 (iFGF23) levels were found." (PMID 26079688, 2015). "Notably, several stimuli couple increased FGF23 transcription with increased post-translational cleavage, including inflammation, iron deficiency, erythropoietin, and parathyroid hormone, resulting in elevated concentrations of circulating total FGF23 but not intact FGF23." (PMID 31487315, 2019). "However, our study could not detect a significant inflammatory state and functional iron deficiency in the higher i-FGF23 tertile." (PMID 28475601, 2017). "If tissue hypoxia is the driver of osteocyte FGF23 gene expression rather than iron deficiency per se these findings may have implications for a number of disease states of chronic hypoxia such as cystic fibrosis and chronic pulmonary disorder (COPD) as well as complications during childbirth." (PMID 26453792, 2016). "Previous studies have shown an increase in FGF-23 cleavage with iron deficiency, driving elevated inactive c-terminal FGF-23, but normal phosphate homeostasis mechanisms are maintained with no change in intact (active) FGF-23 (iFGF-23) levels." (PMID 41445550, 2025). "On the one hand, there are conditions, including iron deficiency, inflammation, and increased erythropoietin (EPO), that stimulate FGF23 transcription and cleavage, resulting in high cFGF23 but normal iFGF23 concentrations." (PMID 37808399, 2023). "Thus, absolute, but not functional, iron deficiency might increase both c-FGF23 and i-FGF23 levels." (PMID 28475601, 2017). "Intravenous iron is widely and extensively used to manage iron deficiency anaemia in people without and with CKD, and effects on circulating FGF23 concentrations have proven variable." (PMID 27852236, 2016). "Lcn2 deletion specifically prevented FGF23 elevations in response to inflammation, but not iron deficiency or phosphate, and administration of LCN2 increased serum FGF23 in healthy and CKD mice by stimulating Fgf23 transcription via activation of cAMP-mediated signaling in bone cells." (PMID 34334787, 2021). "While high FGF-23 C-terminal (cFGF-23) levels may not reflect high intact FGF-23 (iFGF-23), it has been reported that cFGF-23 plasma concentrations increase in women with iron-deficiency anemia." (PMID 37432176, 2023).
secondary hyperparathyroidism (122 papers, 2010 to 2026). Overproduction of parathyroid hormone in response to influence external to the parathyroid glands. "Since elevated levels of FGF23 stimulate the secondary hyperparathyroidism-associated parathyroid αKlotho signaling." (PMID 40394480, 2025). "It was seen that treatment of secondary hyperparathyroidism by administration of cinacalcet resulted in increased hemoglobin levels and was also associated with reduced FGF-23 levels." (PMID 39684548, 2024). "Treatment of secondary hyperparathyroidism with cinacalcet not only improved anemia in HD patients but was also associated with reduced FGF-23 levels." (PMID 39684548, 2024). "The emergence of FGF23 has reformed the understanding of the mechanisms underlying the development of secondary hyperparathyroidism." (PMID 35269640, 2022). "Elevated levels of FGF-23 also exacerbate the deficiency in vitamin D, acting as an additional factor to secondary hyperparathyroidism." (PMID 33579041, 2021). "In CKD, a vitamin D deficiency associated with elevated FGF‐23 levels is thought to represent the initial event in the development of secondary hyperparathyroidism." (PMID 32617522, 2020). "Employing this genetic loss-of-function model, we found that 5/6-Nx induced secondary hyperparathyroidism and bone loss in Fgf23/VDR mice, similar to WT mice." (PMID 29942284, 2018). "Studies using rat CKD (nephritic and 5/6 nephrectomy) models showed that monoclonal-FGF23 antibody injection was associated with a reversal of secondary hyperparathyroidism, increase in serum vitamin D and Ca2+ and normalization of bone markers." (PMID 23760058, 2013). "FGF-23 directly increases urinary fractional excretion of phosphate, impairs the synthesis and accelerates degradation of 1,25(OH)2D and is therefore implicated in the pathogenesis of secondary hyperparathyroidism." (PMID 31185930, 2019). "Using mice with parathyroid-specific knockout of αKlotho or Fgfr genes, we have shown here that FGF23 contributes to the induction of secondary hyperparathyroidism associated with CKD, and that the function of FGF23 in the parathyroid glands is mediated by theαKlotho/FGFR complex." (PMID 28094278, 2017). "However, patients with CKD typically exhibit secondary hyperparathyroidism associated with high serum FGF23 levels, which contradicts the ability of FG23 to suppress PTH secretion." (PMID 24678415, 2014). "Risk factors for CKD–mineral and bone disorder (CKD–MBD) include nutritional vitamin D deficiency, secondary hyperparathyroidism, increased fibroblast growth factor 23 (FGF-23), altered growth hormone and insulin-like growth factor-1 axis, delayed puberty, malnutrition, and metabolic acidosis." (PMID 24605319, 2014). "Another potential mechanism that could link proteinuria with FGF23 levels is secondary hyperparathyroidism, induced by deficiency of vitamin D that accompanies proteinuria." (PMID 22530966, 2012). "Therefore, an increase in plasma FGF‐23 levels as well as a decrease in blood Ca2+ may be responsible for the onset of secondary hyperparathyroidism and may be considered the cause of low BMD in patients with Fabry nephropathy." (PMID 32617522, 2020). "In addition to secondary hyperparathyroidism, FGF23 excess and Klotho deficiency have been recognized as novel factors contributing to vascular calcification which might in part explain the link between CKD progression and atherosclerosis." (PMID 27756244, 2016). "This can lead to secondary hyperparathyroidism and elevated levels of fibroblast growth factor 23 (FGF-23), which, in turn, triggers increased urinary phosphorus excretion as a compensatory mechanism to maintain normal phosphorus balance." (PMID 41601863, 2026). "For example, in CKD, levels of FGF23, a key regulator of phosphate metabolism, increase as kidney function declines, contributing to phosphate excretion and secondary hyperparathyroidism." (PMID 40369127, 2026).
secondary hyperparathyroidism (continued). "MA is a factor leading to a decrease in the level of 1,25-dihydroxyvitamin D3 (calcitriol) in serum and an increase in parathyroid hormone (secondary hyperparathyroidism) and FGF23." (PMID 40870903, 2025). "Disruption of the fibroblast growth factor 23 (FGF23)–Klotho axis and secondary hyperparathyroidism further exacerbate vascular pathology." (PMID 41470171, 2025). "Although increases in FGF23 help to maintain normophosphatemia until late in the course of CKD, FGF23-induced suppression of 1,25-dihydroxyvitamin D contributes to secondary hyperparathyroidism." (PMID 37752381, 2024). "There is also a marked reduction in cutaneous synthesis of 25(OH) vitamin D. High serum FGF-23 levels have now been added to the list of these indicators, which can predict the severity and resistance of secondary hyperparathyroidism in dialysis patients." (PMID 36812096, 2023). "CKD-mineral bone disorder (CKD-MBD) is characterized by abnormalities of bone and mineral metabolism and bone fragility together with increased FGF23, and secondary hyperparathyroidism in CKD patients on dialysis." (PMID 35622784, 2022). "Phosphate retention, low plasma calcium, and high FGF-23 with subsequently decreased plasma Vit D concentration, all contribute to the involvement of secondary hyperparathyroidism." (PMID 36014837, 2022). "Anti-FGF23 treatment was found to significantly improve the bone quality in CKD mice by correcting the secondary hyperparathyroidism, and increased calcitriol levels, indicating that FGF23 is a key factor of CKD related bone diseases." (PMID 35269640, 2022). "This in turn causes maladaptive endocrine changes such as elevation of fibroblast growth factor 23 (FGF23), suppression of 1-alpha hydroxylation in the kidney and development of secondary hyperparathyroidism in humans and reduce longevity." (PMID 31217461, 2019). "The discovery of FGF23 has revolutionized our understanding of secondary hyperparathyroidism and CKD-MBD in general." (PMID 30909513, 2019). "Both treatment regimens will be titrated to equally suppress secondary hyperparathyroidism while alfacalcidol treatment causes an increase and ETL a decrease in FGF23, respectively." (PMID 31651370, 2019). "There is also evidence supporting the reduced Klotho and FGF receptor expression in hyperplastic parathyroid glands, particularly in cases with extremely high FGF23 levels, leading to FGF23 resistance and secondary hyperparathyroidism." (PMID 31637056, 2019). "The discovery of the FGF23/Klotho complex helped to clarify the pathophysiology of secondary hyperparathyroidism." (PMID 30909513, 2019). "As a consequence, compensatory secondary hyperparathyroidism and elevations in fibroblast growth factor-23 (FGF23) occur in order to increase urinary phosphorus excretion and maintain phosphorus balance." (PMID 28394274, 2017). "In conclusion, the rat model with CKD and secondary hyperparathyroidism (CKD group) had high serum FGF-23 levels and high bone turnover." (PMID 26186634, 2015). "In CKD, secondary hyperparathyroidism induces high levels of serum FGF-23, and PTX has shown to decrease elevated FGF-23 levels in advanced secondary hyperparathyroidism in PTX + CKD rats." (PMID 26186634, 2015). "Although disrupted phosphate homeostasis in patients with CKD also induces secondary hyperparathyroidism, the elevation of serum FGF-23 occurs earlier than that of serum PTH levels." (PMID 26186634, 2015). "We believe that elucidation of FGF23-Klotho will provide a different approach in the treatment of refractory secondary hyperparathyroidism." (PMID 25295189, 2014). "In clinical studies, intravenous active vitamin D injection significantly increased serum FGF23 levels in dialysis patients with secondary hyperparathyroidism." (PMID 24678415, 2014).
secondary hyperparathyroidism (continued). "In face of our results, 5/6 Nx model should be employed to study the effects of intervention on blood pressure, on kidney disease progression, on serum levels of PTH, FGF-23 and calcitriol or on mild bone lesions of secondary hyperparathyroidism." (PMID 24885705, 2014). "Dialysis patients with severe secondary hyperparathyroidism who underwent parathyroidectomy showed a decrease in FGF23, and FGF23 levels correlated positively with PTH levels in these patients." (PMID 24625659, 2014). "Some studies reported that high serum FGF-23 levels had an effect in prediction of resistance to vitamin D therapy and refractory secondary hyperparathyroidism." (PMID 25295189, 2014). "Further, their parathyroid sensitivity to acute fluctuations in serum calcium and response to FGF23 treatment were preserved, and mutant mice developed secondary hyperparathyroidism of similar magnitude as wild-type mice when challenged with renal failure." (PMID 24348262, 2013). "Previously, it has been shown that the increased levels of FGF23 in uremia depend upon the degree of secondary hyperparathyroidism and that a feed-back mechanism probably exists with FGF23 also having a regulatory effect on parathyroid function." (PMID 24373521, 2013). "Excessive FGF23 levels, which increase progressively beginning in early stages of kidney disease in order to maintain normophosphatemia despite decreased nephron mass, may be partially responsible for early calcitriol deficiency and secondary hyperparathyroidism in CKD." (PMID 24303131, 2013). "Effective control of serum phosphorus levels alleviates persistent stimulation of the FGF-23–klotho axis, which may subsequently delay the progression of secondary hyperparathyroidism." (PMID 41601863, 2026). "Moreover, cinacalcet reduces serum fibroblast growth factor-23 (FGF-23) levels in patients with secondary hyperparathyroidism (SHPT)." (PMID 40837352, 2025). "Moreover, FGF-23-mediated-reduction 1,25(OH)2D levels lead to secondary hyperparathyroidism, and the rise in PTH further augments renal phosphate excretion." (PMID 40362897, 2025). "This could be due to the presence of secondary hyperparathyroidism in these participants with associated advanced CKD and this could confer a degree of resistance of the parathyroid glands to FGF23." (PMID 38347520, 2024). "Similarly, inhibition of the ERK pathway by FGF23 stimulates the release of PTH in rats with secondary hyperparathyroidism." (PMID 37065733, 2023). "Wolf reported that etelcalcetide potently lowers FGF23 in patients with secondary hyperparathyroidism receiving hemodialysis and that the effect remains detectable among patients who receive concomitant treatments aimed at mitigating treatment-associated decreases in serum calcium." (PMID 35033017, 2022). "Transgenic mice overexpressing Fgf23 display secondary hyperparathyroidism." (PMID 35622784, 2022). "Although higher body fat mass may enhance FGF23 secretion, excessive FGF23 expression may reflect the decreased calcitriol expression or the severe secondary hyperparathyroidism, which in turn, aggravate adipose tissue metabolism leading to reduced fat mass." (PMID 34422722, 2021). "Elevated blood phosphorus can lead to increased levels of PTH and FGF23, the latter being a major regulator of serum phosphorus synthesized and released by osteoblasts, which plays a role in the metabolism of vitamin D and secondary hyperparathyroidism." (PMID 33928079, 2021). "Other factors altered in secondary hyperparathyroidism due to renal failure, such as fibroblast growth factor 23 (FGF-23) and the renin-angiotensin-aldosterone system, may also affect renal function after parathyroidectomy." (PMID 33382714, 2020). "In conclusion, we have found that elevated FGF23 levels in CKD mice stimulate αKlotho/FGFR signalling in the parathyroid glands and induce cell proliferation in these glands, resulting in full-blown secondary hyperparathyroidism associated with CKD." (PMID 28094278, 2017).